FZD4 (frizzled class receptor 4)
Diseases named in the same sentence as FZD4 in open-access papers (continued):
Sharing a sentence is not in itself a finding about the gene and the disease.
bladder cancer (9 papers, 2013 to 2022). "Differential expression of FZD4 has been linked to epigenetic changes in certain cancers, including pancreatic cancer, bladder cancer, and colorectal cancer." (PMID 36170021, 2022). "It was found that miR-493 expression decreased in bladder cancer and overexpressed miR-493 suppressed bladder cancer cells motility through down-regulation of RhoC and FZD4." (PMID 26799283, 2016). "Another miRNA with increased expression is miR-493, which is defined as a tumor suppressor in bladder cancer and is capable of downregulating FZD4 and RhoC protein expression." (PMID 23776562, 2013). "Furthermore, β-catenin and Frizzled Class Receptor 4 (FZD4) are overexpressed in human bladder cancer, and Wnt/β-catenin signaling is activated by FZD4 stimulation, contributing to tumor progression." (PMID 36140796, 2022). "Like other cancers, the expression of miR-101 is significantly reduced in bladder cancer tissue compared with that in adjacent non-tumor tissue, and miR-101 can inhibit bladder cancer cell migration and invasion via directly targeting frizzled class receptor 4 (FZD4)." (PMID 36497343, 2022).
breast carcinoma (7 papers, 2013 to 2023). "The findings also showed that Wnt7b secreted by ATMs may activate the Wnt signaling pathway in the tumor immune microenvironment through interactions with FZD4, ultimately causing malignant transformation of breast cancer." (PMID 34457116, 2021). "Analysis showed that FZD4 was highly expressed in breast cancer tissues compared with normal breast tissues." (PMID 34457116, 2021). "A WNT receptor and a WNT ligand were also dysregulated in breast cancer cell lines, FZD4 showed higher expression in breast cancer cell lines whilst WNT10A expression was decreased." (PMID 23861811, 2013). "Ligand-receptor interactions and potential regulatory mechanisms were explored and the LINC00276&MALAT1/miR-206/FZD4-Wnt7b pathway was identified to play an important role in the functions of these genes and can be used to explore targets against breast cancer metastasis and recurrence." (PMID 34457116, 2021). "The LINC00276&MALAT1/miR-206/FZD4-Wnt7b pathway was identified which may be useful in future research on targets against breast cancer metastasis and recurrence." (PMID 34457116, 2021). "Moreover, ligand-receptor interactions and potential regulatory mechanisms showed that LINC00276&MALAT1/miR-206/FZD4-Wnt7b is a potential pathway in the functions of IMAAGs in breast cancer metastasis and recurrence." (PMID 34457116, 2021). "The LINC00276&MALAT1/miR-206/FZD4-Wnt7b pathway was also identified which may be useful in future research on targets against breast cancer metastasis and recurrence." (PMID 34457116, 2021). "Our independent analysis of primary ER+PIK3CA-mutant breast cancers, which exhibit high INPP4B expression, identified these and additional upregulated Wnt genes (LEF1, MYCN, FZD7, SFRP2, TCF7L1, CTNNB1, FZD4, and SFRP1)." (PMID 34035258, 2021). "This implies that the interaction of Wnt7b and FZD4 between ATMs (CD68+) and adipocytes (FCs) may contribute to the poor prognosis of breast cancer, mainly in the form of a high BCPRS profile." (PMID 34457116, 2021). "PIK3CA mutant ER+ breast cancers exhibit an RNA expression profile of enhanced Wnt/β-catenin signaling, including up-regulation of Wnt target genes (AXIN2, LEF1, MYCN) and other components such as transcriptional regulators (TCF7L1, TCF7L2, CTNNB1), receptors (FZD4, FZD7) and ligands (WNT5A)." (PMID 37471270, 2023).
colorectal cancer (7 papers, 2019 to 2022). A primary or metastatic malignant neoplasm that affects the colon or rectum. "Although studies in premalignant lesions are minimal, FZD4 is known to play a role in mesothelial hyperplasia and Crohn’s disease, a risk factor for colorectal carcinoma." (PMID 34604862, 2021). "The circACAP2 enhances colorectal cancer progression by miR-143-3p/FZD4 signaling." (PMID 35847361, 2022). "CircRNA_100290 also influences colorectal carcinoma (CRC) by inhibiting miR-516b in CRC cells, indirectly upregulating Fzd4 and the Wnt/β-catenin pathway." (PMID 34671643, 2021).
glioma (7 papers, 2013 to 2022). A benign or malignant brain and spinal cord tumor that arises from glial cells (astrocytes, oligodendrocytes, ependymal cells). "Inhibition of Wnt signaling in glioma CSCs leads to loss of stem cell properties while the expression of Fzd4 in glioma cells is associated with increased stemness and invasiveness." (PMID 30510501, 2018). "Genes associated with the neuronal differentiation pathway (Pcsk9, Runx1, Cebpb, Fzd4, Wnt7a, Ascl1, Fzd2, Edn3, Olig2, and Gpc2), gliomas (Shc1, Cdk4, E2f2, and Ccnd1), and cell cycle (Bub1b, Bub, Ccnb1, Ccnb2, and Cdc20) were significantly downregulated." (PMID 36147849, 2022). "FZD4 not only mediated the invasive potential of glioma cells, but also promoted stemness of glioma cells by activating canonical WNT signaling." (PMID 29789460, 2018). "Stemness and invasiveness of migrating glioma cells regulated by Frizzled 4 (FZD4), which promotes expression of the EMT transition regulator SNAI1, are considered as an important mechanism contributing to the failure of this approach." (PMID 23516171, 2013). "For signaling pathways genes, the expression of CXCR4, BIRC5, CTNNB1, FZD4, and MET were significantly increased in high-grade gliomas." (PMID 32154177, 2020).
lung cancer (7 papers, 2011 to 2025). A malignant neoplasm involving the lung. "While FZD3 overexpression was associated with malignancies like lung cancer, FZD4 and FZD10 upregulation was frequently observed in pancreatic and colon cancer, respectively." (PMID 38906870, 2024). "Knockout of Fzd4 in the non‐small cell lung cancer (NSCLC) cell line A549 followed by replenishment of Fzd4 glycosylation site mutants inhibited the growth and migration ability of A549 cells in vitro and in vivo." (PMID 40230079, 2025). "Altogether, FOXF1 increases tumor vessel stability, and inhibits lung cancer progression by stimulating FZD4/Wnt/β-catenin signaling in TECs." (PMID 38589650, 2024). "We have demonstrated that maintaining FOXF1/FZD4 signaling in pulmonary EC via genetic or gene therapy is beneficial to normalize tumor vessels and inhibit lung cancer progression." (PMID 38589650, 2024). "For example, mir-210 regulates ISCU by targeting hypoxia-inducible factors 1 and 2 in renal cancer, and mir-505 inversely regulates FZD4 to modulate cancer proliferation and migration in human lung cancer." (PMID 29715309, 2018).
retinopathy of prematurity (7 papers, 2013 to 2021). A bilateral retinopathy characterized by neovascularization, scarring, retinal detachment, and eventually blindness. "Statistical evidence from studies of patients at risk for the acquired disease retinopathy of prematurity (ROP) suggest that rare polymorphisms in these same genes increase the risk of developing severe ROP, implying that decreased Norrin-FZD4 activity predisposes patients to more severe ROP." (PMID 27489958, 2016). "Pathogenic mutations in NDP and FZD4 could lead to a series of retina-related diseases such as FEVR, Norrie, and retinopathy of prematurity (MIM#133780), which could be distinguished according to their unique characteristics." (PMID 32420371, 2020).
pancreatic cancer (6 papers, 2014 to 2024). "miR-29c is associated with both Fzd4 and Fzd5 in pancreatic cancer." (PMID 34671643, 2021). "DLX6-AS1 also interacts with miR-497-1 via an endogenous sponge mechanism in a FZD4 dependent way, inducing pancreatic cancer cells, migration, and invasion." (PMID 37245177, 2023). "DLX6-AS1 binds miR-497-5p in vitro and increases Fzd4 expression in pancreatic cancer, leading to increased expression of EMT markers." (PMID 34671643, 2021). "miR-29c decreases expression of Fzd4, Fzd5, and frizzled co-receptor LRP6, inhibiting pancreatic tumor cell migration and stemness." (PMID 34671643, 2021). "MiR-29c down-expresses during pancreatic cancer and directly modulates WNT upstream regulators, including FRAT regulator of WNT signaling pathway 2 (FRAT2), frizzled cass receptor 5 (FZD5), lipoprotein receptor-related protein 6 (LRP-6) and frizzled class receptor 4 (FZD4)." (PMID 38559560, 2024).
retinal disease (6 papers, 2016 to 2023). "Pathogenic variants in genes that play key roles within this pathway, such as NDP, FZD4, TSPAN12, and LRP5, have been associated with the incidence of these retinal diseases." (PMID 37947657, 2023). "Therefore defective FZD4 function ought to produce ‘severe’ retinal disease whereas defective LRP5 function ought to produce ‘moderate’ disease." (PMID 35651932, 2022). "This study expands the genotypic spectrum of FZD4 gene in ROP patients, and our findings underscore the importance of obtaining molecular analyses and comprehensive health screening for this retinal disease." (PMID 35022017, 2022).
colon cancer (5 papers, 2007 to 2024). "We also found tumor cell selective expression of the NDP, FZD4, and TSPAN12 genes, encoding norrin, its receptor frizzled 4, and a norrin signal-amplifying component of the receptor complex, respectively, which were linked to colon cancer angiogenesis in a recent study." (PMID 27215396, 2016).
melanoma (5 papers, 2020 to 2025). A malignant, usually aggressive tumor composed of atypical, neoplastic melanocytes. "We therefore chose to focus on FZD4, FZD6, and FZD8 in the further experiments and treated the LECs with either control siRNA or siRNAs targeting the FZD4, FZD6, or FZD8 gene for 24 hours before the start of the 48-hour coculture with WM852 melanoma cells, followed by sorting and functional assays." (PMID 37971882, 2024). "The remaining five receptors (DRD2, FZD4, GPR143, GPR161, and SMO) may be of interest in the context of melanoma, but they have not been studied yet." (PMID 35158973, 2022).
liver cancer (4 papers, 2018 to 2023). An epithelial or non-epithelial malignant neoplasm that arises from the liver. "Low expression of let-7a in liver cancer cells because of its inhibitory effect on the Wnt signaling pathway by regulating Frizzled Class Receptor 4 (FZD4) gene at megakaryocyte development was indicated." (PMID 36140796, 2022). "An in vitro study reported that the Let7b-mediated downregulation of FZD4 inhibited the Wnt/β-catenin signaling, reducing the ratios of liver cancer stem cells and impairing the proliferation, invasion, and migration of liver cancer cells." (PMID 31991677, 2020).
oral squamous cell carcinoma (4 papers, 2020 to 2026). "In addition, the promotion effect of CCL18 on oral squamous cell carcinoma cell proliferation and metastasis by inducing linc00319 expression to regulate miR-199a-5p/frizzled class receptor 4 axis." (PMID 35609322, 2022). "FZD4 has been demonstrated to regulate LINC00319-induced proliferation and metastasis in oral squamous cell carcinoma." (PMID 39735608, 2024).
Vitreoretinopathy (4 papers, 2015 to 2021). Ocular abnormality characterized by premature degeneration of the vitreous and the retina that may be associated with increased risk of retinal detachment. "A study of 421 patients with various vitreoretinopathies found significant correlations between the FZD4 double missense mutation and both ROP and FEVR." (PMID 32884843, 2020). "For FZD4, it was shown that dimerization occurs in the ER and that FZD4 mutants associated with vitreoretinopathy can retain wt FZD4 in intracellular compartments." (PMID 28790300, 2017).
Blindness (3 papers, 2015 to 2025). Blindness is the condition of lacking visual perception defined as a profound reduction in visual perception. "Treatments that aim to alter Norrin-Fzd4 signaling may decrease the risk of blindness in prematurely born infants by reducing the vulnerable time period during which blinding complications can occur." (PMID 27489958, 2016).
cervical carcinoma (3 papers, 2018 to 2021). A carcinoma arising from either the exocervical squamous epithelium or the endocervical glandular epithelium. "Fzd4 has exhibited tumorigenic properties in studies of bladder, prostate, glioma, lung, liver, pancreatic, and cervical carcinoma by supporting proliferation, tumor progression, and metastasis through upregulation of canonical Wnt signaling." (PMID 34671643, 2021). "Overexpression of miR-505 suppressed the proliferation and invasion of cervical cancer cell via targeting Frizzled-4 (FZD4)." (PMID 31160483, 2019). "Additionally, several reports have indicated that miR-505 plays a suppressor role in cervical carcinoma by targeting the Frizzled-4 gene (FZD4) and in endometrial cancer by targeting transforming growth factor-α (TGF-α)." (PMID 29651425, 2018).
Coats disease (3 papers, 2013 to 2022). Coats disease (CD) is an idiopathic disorder characterized by retinal telangiectasia with deposition of intraretinal or subretinal exudates, potentially leading to retinal detachment and unilateral blindness. "Furthermore, vascular abnormalities in the retina, also known as Coats disease, are phenotypically similar to familial exudative vitroretinopathy (FEVR), recently linked to mutations in the Wnt receptor Frizzled4 (FZD4) and its ligand Norrin." (PMID 23785297, 2013).
diabetic retinopathy (3 papers, 2021 to 2025). "Our observation that F4L5.13 resolves CE further validates the norrin/FZD4 signaling pathway as a compelling target for drug development in ME, for example in diabetic retinopathy, age-related macular degeneration, or retinal occlusive disease." (PMID 41086024, 2025). "Similarly, F4L5.13, a tetravalent diabody with a dumbbell-like structure, has also been found to demonstrate comparable results in the treatment of diabetic retinopathy by acting against FZD4 and LRP5 receptors and LRP5 signaling." (PMID 40940800, 2025). "SZN-413, a FZD4/LRP5-targeting Norrin mimetic molecule, is an essential therapeutic option for diabetic retinopathy." (PMID 40940800, 2025). "FZD4/LRP5 agonists also reduce neovascular tufts in mice with oxygen-induced retinopathy; therefore, this class of agonists appears to target multiple processes relevant to diabetic retinopathy, including promoting BRB function and reducing pathological neovascularization." (PMID 41086024, 2025).
non-small cell lung carcinoma (3 papers, 2020 to 2021). A group of at least three distinct histological types of lung cancer, including non-small cell squamous cell carcinoma, adenocarcinoma, and large cell carcinoma. "FZD4 also contributes to EMT in non-small cell lung cancer (NSCLC) both in vitro and in vivo by activating the TCF/LEF/WNT/β-catenin pathway." (PMID 34604862, 2021). "Downregulation of miR-3127-5p promotes epithelial-mesenchymal transition through activating the Wnt/FZD4/β-catenin pathway in non-small-cell lung cancer." (PMID 32194636, 2020). "For example, it has been reported that miR-3127 directly targets FZD4, thereby activating the Wnt/β-catenin signaling pathway in non-small-cell lung cancer." (PMID 32194636, 2020). "In non-small-cell lung cancer, reduction of miR-3127-5p accelerated EMT via activating the Wnt/FZD4/β-catenin signaling pathway." (PMID 34226533, 2021).
osteoporosis (3 papers, 2018 to 2021). A condition of reduced bone mass, with decreased cortical thickness and a decrease in the number and size of the trabeculae of cancellous bone (but normal chemical composition), resulting in increased fracture incidence. "Since this miRNA is upregulated in the serum of osteoporosis patients, it negatively controls the FZD4 expression, thus impeding the osteogenic differentiation of human BMSCs and promoting the progression of osteoporosis." (PMID 35011442, 2021). "Our data reveled that Ps-GOS significantly up-regulates the expression of Wnt5a, LRP5, β-catenin, and Fzd4 mRNA, in MC3T3-E1 cells, suggesting that Ps-GOS may prevent bone loss in osteoporosis through Wnt/β-catenin together with BMP-2 signaling pathways." (PMID 32012654, 2020).
acute lymphoblastic leukemia (2 papers, 2022 to 2024). Leukemia with an acute onset, characterized by the presence of lymphoblasts in the bone marrow and the peripheral blood. "FZD7 and FZD8 are expressed in most acute lymphoblastic leukemia (ALL) cells, while FZD3, FZD4, and FZD9 are occasionally detected." (PMID 36452482, 2022).
developmental delays (2 papers, 2022). "A case series detected a heterozygous biallelic variant in FZD4 leading to hearing deficits and developmental delays." (PMID 36411543, 2022). "The decrease in FZD4 signaling owing to the biallelic nature of the disease resulted in hearing deficits, developmental delays, and a more severe retinal phenotype." (PMID 35951321, 2022). "In this case series investigation, a syndrome was presented that was associated with biallelic variants in the FZD4 gene and early-onset severe FEVR accompanied by hearing loss and developmental delay." (PMID 35951321, 2022). "This case series included a patient with biallelic FZD4 variants with severe FEVR in infancy, congenital hearing loss, and developmental delay." (PMID 35951321, 2022). "This case series identified a patient with biallelic FZD4 variants, severe FEVR, and an extraocular phenotype, including sensorineural hearing loss and developmental delay, potentially associated with a new syndrome." (PMID 35951321, 2022). "Frizzled-4 (FZD4) variants can result in hearing deficits and developmental delays." (PMID 36411543, 2022).
gastric cancer (2 papers, 2021). A primary or metastatic malignant neoplasm involving the stomach. "GATA6-AS1 induces hypermethylation of the Fzd4 promoter region via EZH2 recruitment in gastric cancer, inhibiting Fzd4 expression and reversing EMT." (PMID 34671643, 2021).
hepatoma (2 papers, 2022 to 2023). "In mammals the parasite-derived miR-71 targeting of the frizzled pathway gene FZD4 inhibits hepatic cell signaling and can exert antitumor effects on hepatoma cells." (PMID 37624033, 2023). "By negatively regulating the expression of the frizzled pathway protein FZD4 miR-71 effectively arrested hepatoma cells at the G0/G1 phase and inhibited the migration of tumor cells in mouse liver." (PMID 37624033, 2023). "In this study, we demonstrated that downregulation of FZD4 in hepatoma cell by the FZD4 siRNA inhibited the cell growth and migration, similar to the Sja-miR-71a-mediated antitumor activity." (PMID 35174106, 2022). "We found that Sja-miR-71a, an S. japonicum miRNA, can arrest hepatoma cell cycle at G0/G1 phase and inhibited migration of tumor cells by targeting the FZD4 gene." (PMID 35174106, 2022). "In the present study, we demonstrated that a specific S. japonicum miRNA, Sja-miR-71a, which exists in host liver cells during infection, has anti-tumor effect on hepatoma cells through suppression of growth and migration of tumor cell by cross-species regulation of FZD4 gene." (PMID 35174106, 2022).
lung adenocarcinoma (2 papers, 2017 to 2022). A carcinoma that arises from the lung and is characterized by the presence of malignant glandular epithelial cells. "Based on the TCGA data, we constructed a lung adenocarcinoma prognosis model, and we found five key Wnt signaling pathway related genes, including AXIN1, CTNNB1, LEF1, FZD2, FZD4." (PMID 36703749, 2022).
myopia (2 papers, 2025). "Interestingly, we found that myopia was a common finding among FZD4 variant‐positive individuals." (PMID 38706142, 2025). "It implied that when the FZD4 gene is inactivated as a variant, the function of the LRP2 protein will be affected, which may be potentially responsible for high myopia." (PMID 41477247, 2025). "FZD4 is another key factor activating the Wnt pathway, which contributes to myopia." (PMID 41477247, 2025).
prostate tumor (2 papers, 2011 to 2018). "Frizzled-4 (FZD4, a Wnt receptor) is co-expressed in human prostate tumor samples with the ETS-related gene (ERG)." (PMID 24212796, 2011).